APOB (apolipoprotein B)
Diseases named in the same sentence as APOB in open-access papers (continued):
Sharing a sentence is not in itself a finding about the gene and the disease.
atherosclerosis (continued). "GSTT1, encoding Glutathione S-Transferase Theta 1, is an enzyme involved in the cellular defense against oxidative stress and genetic variants in this gene have been associated with risk for diabetes and atherosclerosis, and plasma total cholesterol, LDL-C and apolipoprotein B levels." (PMID 33096472, 2020). "In summary, our results corroborated that genetic variations in apolipoprotein B affected the lipemic profile of Brazilian elderly individuals living in urban conditions and may contribute to atherosclerosis." (PMID 32130292, 2020). "Finally, we detected that plasma CCDC80 level was positively associated with the dyslipidemia and atherosclerosis marker LDL-C, apoA1 and apoB." (PMID 31992220, 2020). "However, overexpression of biglycan in mice increased arterial retention of apoB lipoproteins and promoted atherosclerosis." (PMID 33352066, 2020). "In addition, the chemical composition and cholesterol ester transfer subunits of human and rabbit ApoB-related lipoproteins are similar, which correlates with the role of rabbit ApoB in atherosclerosis." (PMID 33054837, 2020). "Moreover, T2DM patients with DPN had significantly higher levels of blood pressure, blood glucose, surrogate markers of atherosclerosis including increased ApoB/ApoA and coagulation index, reduced ApoA, and lower ABI values." (PMID 31827625, 2019). "HD patients display advanced atherosclerosis that is associated with nontraditional risk factors (ApoB)." (PMID 31915710, 2019). "In CKD patients, the ApoB/ApoA-I ratio reflects the cholesterol balance between atherogenic and antiatherogenic lipoprotein particles, and an increased ratio highlights the progression of atherosclerosis." (PMID 31915710, 2019). "ApoB vaccination promotes Th2 responses that reduce atherosclerosis." (PMID 31653058, 2019). "Having found significant associations of two SNPs with LDL-cholesterol and apolipoprotein B levels, we set out to explore whether these SNPs were associated with IMT of the common carotid artery, a known early marker of atherosclerosis." (PMID 29773828, 2018). "The expression change of APOA4 and APOB in human atherosclerosis was more similar to rabbit, and therefore rabbit might be a better animal model for investigating human lipoprotein metabolism related diseases." (PMID 30067832, 2018). "Due to the similarity between CAS and atherosclerosis, the apoB gene may also effect the initiation of CAS." (PMID 29514644, 2018). "However, the relationship between apoB and metabolic diseases is more complicated than just apoB48 (edited) leading to diabetes/obesity and apoB100 (unedited) leading to atherosclerosis." (PMID 30619092, 2018). "Furthermore, the apoB/apoA ratio was recently recognized as the best predictor for atherosclerosis among all cholesterol indicators." (PMID 29018401, 2017). "that atherosclerosis signaling may relate to the aging of arterial and be inhibited by controlling the target ApoB." (PMID 28031022, 2016). "This study tested the hypothesis that increased hepatic ceramide and sphingolipid production contributes to the pathogenesis of diet induced NAFLD and atherosclerosis through modulation of lipogenesis and ApoB and ApoAI metabolism." (PMID 25993337, 2015). "The apolipoprotein B-100 (ApoB-100) transgenic mouse line is a model of human atherosclerosis." (PMID 26184769, 2015).
atherosclerosis (continued). "Among patients with carotid atherosclerosis, men were found to be younger than women, which may be the result of a lower level of apoB, as apoB protects against the development of atherosclerosis, and is a good predictor of CVD." (PMID 25885111, 2015). "The genetic variation in USF1 influence USF1 transcript expression in advanced atherosclerosis and regulates levels and metabolism of circulating apoB and apoB-containing lipoprotein particles in sex-dependent manner, but is not a major determinant of early markers of atherosclerosis." (PMID 24722012, 2014). "However, we found that several risk factors of atherosclerosis, such as the level of TG, APOA and APOB, had a relationship with the polymorphisms of ICAM-1 in coronary atherosclerosis cases." (PMID 25310099, 2014). "Pharmacologic inhibition of SMS may be a new therapy for atherosclerosis by reducing apoB secretion, and reducing inflammation." (PMID 25032960, 2014). "Furthermore the superiority of apoB over LDL-cholesterol as predictor of subclinical atherosclerosis, is in line with previous observational studies." (PMID 23536999, 2013). "Serum apoB and the apoB/apoA-I ratio might be independent predictors of early atherosclerosis in NGT." (PMID 23359805, 2013). "Because of the beginning of the atherosclerosis' process from early life, in this study, the plasma levels of apoA1 and apoB were compared in diabetic children with type I diabetes mellitus(DM), healthy children with diabetic parents (HDPs),and healthy children with nondiabetic parents (HNDPs)." (PMID 22811893, 2012). "During the pathogenesis of atherosclerosis, blood monocytes infiltrate from blood to the intima and subintima, a process which is activated by subendothelial accumulation of apolipoprotein B-containing lipoproteins (apoB-LPs)." (PMID 22577254, 2012). "Thus, immunizations with both ApoB peptides as well as oxidized phospholipids have atheroprotective effects in animal models of diet-induced atherosclerosis." (PMID 22957222, 2012). "Thus for primordial and primary prevention of atherosclerosis, we suggest screening these children for low plasma apoA1 and high plasma apoB levels." (PMID 22811893, 2012). "Other lipid precursor proteins such as ApoB and ApoA-I may be stronger predictors of subclinical atherosclerosis, however, and better targets for treatment to reduce plaque formation and risk of cerebrovascular disease." (PMID 20028534, 2009). "Because of its central role in atherosclerosis, APOB has become a major therapeutic target." (PMID 17233885, 2007). "In a second study the phenotype of ApoA-I or ApoA-IM knock-in mice on an atherosclerosis prone ApoB/ApoAII background was analyzed with the finding of a less favorable lipid profile and a more pronounced atherosclerosis development in female ApoA-IM knock-in mice." (PMID 17475009, 2007). "Five of them (ANGPTL4, APOB, BRAP, LPA, and ZPR1), were associated with increased levels of arteriosclerosis/atherosclerosis and risk of CVD, whereas four (DUSP13, FN1, IL6R, and MMP12) were associated with reduced levels of arteriosclerosis/atherosclerosis and risk of CVD." (PMID 42133815, 2026). "Since atherosclerosis is highly influenced by the total time of exposure to a certain level of atherogenic particles, pre-statin apoB levels might have offered a greater accuracy and may have better captured the true magnitude of the risk inflicted by this lipoprotein." (PMID 41374382, 2025). "Thus, ApoB drives the development of atherosclerosis by ferrying cholesterol into arterial plaques." (PMID 40944180, 2025).
atherosclerosis (continued). "Other indicators, such as the apolipoprotein B to apolipoprotein A-I ratio (ApoB/ApoA-I) and coronary artery calcium scores, may provide more accurate assessments of atherosclerosis severity, but their clinical utility remains limited due to high testing costs and low accessibility." (PMID 40687558, 2025). "In the absence of a mutation in the gene encoding LDL receptor or apolipoprotein B (APOB), certain families were found with the diagnosis of familial hypercholesterolemia (FH), an autosomal codominant genetic disorder characterized by elevated levels of LDL‐C and early atherosclerosis." (PMID 39479289, 2024). "Increased ApoB levels have been associated with an increased risk of atherosclerosis and cardiovascular disease in non-pregnant populations, and these alterations may likewise have implications for pregnant women." (PMID 37763183, 2023). "Similarly, ApoB, the primary apolipoprotein of chylomicrons and low-density lipoproteins, has a well-established role in promoting cholesterol deposition in arterial walls, leading to atherosclerosis." (PMID 37763183, 2023). "Furthermore, arterial wall deposition of ApoB runs through the whole process of atherosclerosis." (PMID 37047284, 2023). "Men with an android percent fat less than 30.1% and a plasma ApoB level greater than 100.57 mg/dL, and women with a gynoid percent fat less than 39.9% and a plasma ApoB level greater than 93.65 mg/dL, should receive appropriate guidance for preclinical atherosclerosis." (PMID 37047284, 2023). "Apolipoprotein B (ApoB) can be detected in LDL, very low-density lipoprotein (VLDL), chylomicron and lipoprotein(a)s in plasma and leads to the risk of peripheral artery disease and coronary artery disease by depositing in the arterial wall throughout the whole process of atherosclerosis." (PMID 37047284, 2023). "While the typical percept is that autoimmunity can be pathogenic per se, the present proof indicates that ApoB-specific CD4+ T-helper cells have already been determined among subjects without clinical atherosclerosis and with atheroprotective characters mostly." (PMID 35663954, 2022). "Dyslipidemia is one of the most important triggers of atherosclerosis in the arterial wall and ASCVD, which is characterized by abnormal elevated levels and deposition of apolipoprotein B, including LDL-C." (PMID 35983485, 2022). "Moreover, hepatic overexpression of miR-30c remarkably decreased atherosclerosis through the downregulation of cholesterol and ApoB-lipoprotein synthesis in a hyperlipidemic mouse model, while inhibition of microRNA-30c induced dyslipidemia and atherosclerosis." (PMID 33953838, 2021). "We identified the ApoB:ApoA1 ratio as a potential predictive biomarker of increased CVD risk in patients, who shared a serum metabolomic profile with adult SLE patients with sub-clinical atherosclerosis and a T-cell phenotype with T-cells isolated from human atherosclerotic plaque." (PMID 35050125, 2021). "Atherosclerosis is a disease characterized by low-grade and chronic inflammation of the arterial wall which is triggered by subendothelial retention of plasma-derived apolipoprotein B (apoB)-containing lipoproteins in the inner layer of the arterial wall, the intima." (PMID 33616800, 2021). "Interestingly, ApoB p6-reactive T helper cells isolated from immunized mice and transferred to donor mice promoted atherosclerosis in abdominal aortas, while vaccination with p6 prevented atherosclerosis in Apoe−/− mice in another report." (PMID 33669769, 2021). "Thus, our findings are in keeping with established understanding of the development of atherosclerosis but pinpoint the crucial role of apolipoprotein B in the pathogenesis as a key molecule facilitating the entrapment of atherogenic lipoprotein particles in the intima." (PMID 32203549, 2020).
atherosclerosis (continued). "The increase of ApoB or decrease of apoA1 indicates the increase of cholesterol transport to peripheral tissues or decrease of cholesterol transport back to liver, leading to more cholesterol deposition on the blood vessel wall and promoting the occurrence of atherosclerosis (AS)." (PMID 32539722, 2020). "Therefore, increased ApoB/ApoA1 ratio exacerbating the atherosclerosis and inflammation of intracranial vascular might explain our findings of a correlation of the ApoB/ApoA1 ratio with RN volume." (PMID 32017458, 2020). "For example, a naïve interpretation of our findings would be that apolipoprotein B confounds the relationship of LDL cholesterol and triglycerides with risk of CHD, but this would be to neglect evidence gleaned over a century of scientific investigations into atherosclerosis." (PMID 32203549, 2020). "The infiltration of apolipoprotein B (apoB) containing lipoproteins within the vessel wall, release of inflammatory cholesterol crystals, and the development of fatty streaks are features of early atherosclerosis, but their influence on central arterial stiffening is not known." (PMID 32411471, 2020). "In a previous study, we have found that the BRCA2 rs9534275 SNP modulated serum TC, LDL-C, ApoB concentrations, and the ApoA1/ApoB ratio in the hypercholesterolemic subjects, suggesting that the rs9534275 SNP plays an important role in the formation of atherosclerosis." (PMID 28982360, 2017). "Atherosclerosis usually occurs in the intima of medium-sized arteries at regions of disturbed blood flow, which is triggered by an interaction between endothelial dysfunction and subendothelial retention of apolipoprotein B- (apoB-) containing lipoproteins (LPS) in focal areas of arteries." (PMID 29038615, 2017). "When the balance between apoB-reactive effector T cells and Tregs is shifted in favour of the effector T cells, a local loss of tolerance against LDL in the plaque could aggravate atherosclerosis." (PMID 26840480, 2016). "Epidemiological studies have shown an association between apoB gene polymorphisms and generalized and regional obesity and an increase in various lipoprotein subfractions (total cholesterol [TC], low density lipoprotein cholesterol [LDL-C], triglyceride [TG]), and atherosclerosis." (PMID 25889118, 2015). "Taken together, the data suggest that after Lp-PLA2 is bound to LDL via apoB, lysophosphatidylcholine and free oxidized fatty acids, two strong pro-inflammatory factors, are produced through the hydrolysis and oxidation of phospholipids, thereby promoting chronic inflammation and atherosclerosis." (PMID 24393260, 2014). "Atherosclerosis is defined as an inflammatory disease and previous studies have demonstrated positive associations between PAD and inflammatory markers, including high-sensitivity C-reactive protein (hsCRP), fibrinogen, homocysteine and apolipoprotein B (apo B)." (PMID 23737897, 2013). "Among those who did, imaging-based evaluation of subclinical atherosclerosis was the most frequently selected approach, followed by Lp(a) and triglycerides, hs-CRP, and apoB." (PMID 42279067, 2026). "The KEGG path view suggests that LBP, MMP9, APOB, IL6, and RAP1B are involved in lipid metabolism and atherosclerosis." (PMID 41221287, 2025). "ApoB is a crucial component of LDL-C, and its deposition within the arterial wall is a fundamental step driving the progression of atherosclerosis, from initial lipid deposition to the development of acute complex events, such as plaque rupture." (PMID 39851250, 2025). "ApoB carries LDL cholesterol into the arterial wall and, after oxidation, it is phagocytosed by macrophages, generating foam cells and thus leading to atherosclerosis." (PMID 39291781, 2025).
atherosclerosis (continued). "Thus, on day 21 of HDBR, the levels of RBP4, APOB and C3 proteins increased, each of which plays an important role in one way or another in modulating the properties of the endothelium and contributing to the development of atherosclerosis, which is a precursor of many cardiovascular diseases." (PMID 38966226, 2024). "By recognizing the core proteins of ApoB and LDL, immune cells led to atherosclerosis that similar with an autoimmune manner." (PMID 38992867, 2024). "Other studies revealed the presence of ApoB-specific CD4 T cells in mice and patients with atherosclerosis." (PMID 39669576, 2024). "Dysregulated hepatic production of apolipoprotein B (APOB)-containing very LDL (VLDL) particles is a central determinant of plasma lipoprotein levels and development of atherosclerosis." (PMID 38833612, 2024). "This study evaluated the correlations between atherosclerosis-related lipid parameters and LDL/ApoB < 1.2 in male vs. female patients with DM." (PMID 39420941, 2024). "A study of Women’s Health Across the Nation (SWAN) found that TC, LDL-C, and apolipoprotein B (Apo B) demonstrated substantial increases within the 1-year interval before and after menopause, independent of the age of menopause, which could further lead to endothelial injury and atherosclerosis." (PMID 39902165, 2024). "Thus, targeting the liver ApoB could have beneficial effects on reducing atherosclerosis." (PMID 39332527, 2024). "We recently reported the identification of six T-cell epitopes in human APOB, the core protein component of LDL, and a well-studied atherosclerosis antigen." (PMID 38571941, 2024). "The identified APOB-reactive expanded CD4+T cell clones and conserved motifs can be used to annotate and track human atherosclerosis-related autoreactive CD4+T cells and measure their clonal expansion." (PMID 38571941, 2024). "Familial hypercholesterolemia type 2 (FHCL2) (OMIM 14401014), also called familial defective apolipoprotein B-100 (FDB), is an autosomal dominant disorder manifested by increased plasma lipids level and early onset of atherosclerosis." (PMID 37510094, 2023). "Four weeks of mAb2 treatment under lipid-lowering conditions reduced atherosclerosis in en face aorta and the BCA, and apoB content, macrophage infiltration, plaque necrosis, collagen content and fibrous cap thickness in the BCA." (PMID 39196046, 2023). "ApoB reactive (ApoB+) CD4 T cells have mixed phenotypes in healthy mice and humans that undergo dynamic changes in the course of atherosclerosis development." (PMID 36684560, 2022). "Levels of plasma cholesterol, LDL, and apolipoproteins including Apolipoprotein B (ApoB), the protein backbone of LDL, correlate with clinical atherosclerosis." (PMID 35479271, 2022). "While the interplay between apoB and IC remains to be elucidated, it is suggested that apoB-specific CD4 T cells can drive autoimmunity in atherosclerosis." (PMID 36263134, 2022). "It was further demonstrated that HSP60 serum levels correlate with the total cholesterol, LDL, and ApoB and negatively with adiponectin, and the intensity of HSP expression also correlates positively with the severity of atherosclerosis." (PMID 36003652, 2022). "In the early phase of atherosclerosis, dysfunctional arterial endothelial cells allow LDL to enter the endothelial layer and then adhere to intimal proteoglycans by way of ApoB, where it accumulates gradually in the intimal layer." (PMID 35712827, 2022). "Apolipoprotein C3 (ApoC3), a surface protein component abundantly found on circulating triglyceride-rich ApoB lipoproteins and HDL, is a major contributor to atherosclerosis, according to increasing evidence." (PMID 35453604, 2022).